GDF15 (growth differentiation factor 15)
Diseases named in the same sentence as GDF15 in open-access papers (continued):
Sharing a sentence is not in itself a finding about the gene and the disease.
tumor (continued). "Furthermore, Il-6 mRNA expression at the tumor site was increased 2-fold in Cx- compared to pre-Cx mice, while Gdf15 mRNA level remained unchanged." (PMID 40124481, 2025). "Gene expression levels of DJ-1, GDF15, and MFGE8 were increased in tumours larger than 6 cm in diameter, with the most prominent and statistically significant increase observed in the GDF15 gene (p = 0.556, p = 0.042, and p = 0.053 for DJ-1, GDF15, and MFGE8, respectively)." (PMID 41009755, 2025). "Evidence has shown that GDF15 has been proved to enhance tumor cell proliferation." (PMID 40144214, 2025). "GDF15 has been recently identified as a promoter of tumor progression." (PMID 40775002, 2025). "At the protein level, GDF15 expression, assessed by immunohistochemistry (IHC), revealed primarily cytoplasmic staining at any level of expression intensity in tumor tissues and non-tumor tissues adjacent to the tumor." (PMID 40725563, 2025). "However, when GDF15 was silenced in CAFs, the pro-migratory effect of SM-1 was significantly attenuated, indicating that SM-1 exerts its tumor-promoting effects through a GDF15-dependent mechanism." (PMID 41035818, 2025). "In contrast with other studies, GDF15 levels were not influenced by clinical risk factors such as tobacco and alcohol habits, nor by tumor size, tumor stage, and cervical lymph node metastasis, but potentially correlated with the grade of differentiation." (PMID 40868185, 2025). "While limited data are available on the correlation between malignant tissue and its matched neighbouring benign tissue, some studies have shown that an elevated level of GDF15 in tumour tissue, compared to adjacent benign regions, has been found to increase the risk of PCa recurrence." (PMID 39578642, 2025). "RNA-Seq sequencing identified strong evidence of gene modulation linked to metastasis (such as GDF15) by LINC01133, along with reciprocal regulation of LINC01133 expression by GDF15, identified through GDF15 silencing assays in CAL27, HN4, and 293FT tumor cell lines." (PMID 40863724, 2025). "Furthermore, we employed siRNA to knockdown of GDF15 expression in GC cells and assessed the chemotactic effect of the tumour cell supernatant on CAFs." (PMID 40292733, 2025). "GDF-15 negatively affects tumour immunity, suggesting that anti-GDF-15 therapy could potentially enhance immune responses and help overcome resistance to immunotherapy." (PMID 41294666, 2025). "GDF15 is responsive to metabolic stress and may reflect treatment toxicity as much as tumor biology." (PMID 41009692, 2025). "Next, we evaluated the paracrine effect of CAF-derived GDF15 on tumor cells." (PMID 41035818, 2025). "Overview of GDF15’s potential biological role across various tumor types." (PMID 40868185, 2025). "Finally, the small-molecule compound SM-2 inhibits the malignant behavior of tumor cells by blocking the binding of GDF15–GFRAL." (PMID 41035818, 2025). "In initial tumor specimens, GDF-15 expression was rare and predominantly confined to tumor cells." (PMID 41994030, 2025). "The treatment increased tumor infiltration and activity of cytotoxic T cells, suggesting GDF-15 inhibition could help overcome resistance to immune checkpoint inhibitors." (PMID 40001572, 2025). "Furthermore, GDF-15 has been shown to inhibit T cell infiltration into the tumor microenvironment, potentially reducing the efficacy of immunotherapy." (PMID 40144214, 2025). "Notably, GDF15 has been shown to exhibit dual roles during carcinogenesis, inhibiting tumor growth in the initial stages while promoting proliferation in later stages." (PMID 39083441, 2025). "In vitro, co-culture of macrophages with tumor cell supernatants demonstrated upregulation of M2 polarization markers by qRT-PCR and increased M2/M1 ratio by flow cytometry, confirming that GDF15 promotes M2 macrophage polarization and infiltration in GBM." (PMID 41281763, 2025).
tumor (continued). "Additionally, TAMs secrete growth differentiation factor 15 (GDF15), which promotes tumor cell adaptation to oxidative stress and chemotherapeutic toxicity." (PMID 41002423, 2025). "However, post-experiment analysis revealed that the NAG-1/GDF15 WT and NAG-1/GDF15 R193A groups exhibited smaller tumor size, volume, and weight, with less redness compared to the control group." (PMID 40316530, 2025). "Therefore, the regulation of GDF-15 by MYC also promotes the escape of tumor cells from macrophage attack." (PMID 40732268, 2025). "The heavily pretreated population with immune-exhausted tumour microenvironments could also have limited the immunomodulatory potential of GDF-15 blockade." (PMID 41294666, 2025). "Additionally, elevated GDF15 was positively correlated with larger tumor size (p < 0.0001), presence of microvascular invasion (p = 0.026) and abnormal AST levels (p = 0.001)." (PMID 40677718, 2025). "Moreover, it is possible that CCL2, CCL5, CCL18, TGFB1, and GDF15 are also produced by cells other than the VS tumor cells." (PMID 39272860, 2024). "Plasma IL-6 and GDF-15 were both increased at around two weeks following tumor inoculation." (PMID 38824130, 2024). "Inhibition of GDF-15 or its downstream effectors may help inhibit tumor growth, metastasis, and chemoresistance in PDAC." (PMID 39575418, 2024). "Meanwhile, the suppression of tumor growth by sh-GDF15 was validated in vivo level." (PMID 38230211, 2024). "This is the only tumor model in which the pathway GDF-15/GFRAL has been demonstrated." (PMID 39000420, 2024). "However, in the context of tumors, the data on the effect of GDF-15 are controversial, with some authors suggesting its carcinogenic activity and others pointing to its tumor suppressor activity." (PMID 38668313, 2024). "In osteoblastic bone metastasis, tumor cells release diverse elements, including endothelin-1 (ET-1), growth differentiation factor 15 (GDF15), and bone morphogenetic protein (BMP) which stimulate the proliferation and differentiation of osteoblasts principally via the Wnt signaling pathway." (PMID 38243240, 2024). "Furthermore, the potential paracrine effect of macrophages producing GDF-15 in the tumor microenvironment expressing GFRAL should also be explored." (PMID 39000420, 2024). "GDF-15 expression is epigenetically regulated in several tumor cell lines." (PMID 38335385, 2024). "GDF-15 contributes to an immunosuppressive tumor microenvironment by inhibiting T-cell activation, which may reduce the effectiveness of immune checkpoint inhibitors." (PMID 39766045, 2024). "Tumor growth was concordantly decreased by GDF-15 knock down (KD)." (PMID 39000420, 2024). "Elevated GDF15 levels are observed in inflammation, myocardial ischaemia and tumours." (PMID 39156689, 2024). "Treatment of tumor bearing mice with WFA showed a decrease in GDF-15 levels." (PMID 39394174, 2024). "Our results showed a significant increase in levels of expression of inflammatory cytokine IL-1 β (p < 0.01), IL-6 (p < 0.001), TNF-α (p < 0.001), and other related genes including TRAF6 (p < 0.01), MYD88 (p < 0.01), and GDF-15 (p = 0.005) in tumor-bearing mice compared to controls." (PMID 39394174, 2024). "In addition, nuclear factor (NF)-κB can directly regulate GDF15 to evade macrophage surveillance during the early stages of tumour development." (PMID 37093513, 2024). "They showed that GDF15 knockdown decreased F-actin polarization and thereby tumor invasion." (PMID 39000420, 2024). "The previous study revealed that GDF15 can promote immunosuppression in the tumor microenvironment." (PMID 38704691, 2024). "The concentration of the cytokine GDF15 correlated with tumor volume, suggesting that this cytokine could have an impact on tumor progression." (PMID 39272860, 2024).
tumor (continued). "Moreover, the amount of GDF15 in the cell culture supernatant of primary cells correlated positively with tumor volume." (PMID 39272860, 2024). "High expression of ANXA2, TREM2, TTC39A, and GDF15 may lead to a more suppressive tumor microenvironment and enhanced immune escape, thereby reducing the efficacy of immunotherapy." (PMID 39697329, 2024). "However, a direct correspondence between the presence of GDF-15 in the tumor microenvironment and squamous cell carcinoma progression has not been established." (PMID 39000420, 2024). "In addition to the secretion of soluble GDF15 proteins, tumor cells also released GDF15-containing extracellular vesicles which promoted muscle atrophy/cachexia." (PMID 39643709, 2024). "In vivo validation confirmed sh-GDF15's tumor growth suppression, reinforcing our conclusions." (PMID 38230211, 2024). "Also, high levels of GDF-15 in the tumor microenvironment, produced by both esophageal cancer cells and macrophages, are associated with more malignant phenotypes." (PMID 39000420, 2024). "This suggests that alternative mechanisms to limit GDF-15 secretion might be activated in the tumor cell, as an adaptation to ZBTB18 reduction." (PMID 39516530, 2024). "Similarly, it was shown that IR regulates GDF15 expression by cells in the tumor microenvironment, including macrophages, fibroblasts, or endothelial cells." (PMID 38201456, 2023). "Correlations between GDF-15 serum levels and tumor size were weaker than expected." (PMID 37474523, 2023). "Since GDF15 is not only secreted by tumor cells but also is affected by various immune cells, and immunotherapy targets T cells, it may be more useful to measure GDF15 at the circulating level." (PMID 36472770, 2023). "The depletion of tumor-derived GDF15—directly regulated by NF-κB—in an orthotopic pancreatic cancer model restored the immune surveillance function of tumor-infiltrating macrophages, resulting in improved tumor control." (PMID 36472770, 2023). "Furthermore, depletion of CD8 T cells in tumor-bearing mice eliminated the protective effect of GDF15 against tumor growth." (PMID 37860011, 2023). "Results from Cell Counting Kit-8 (CCK-8) assay demonstrated that 769-p and Caki-1 cells with decreased GDF15 expression had enhanced viability compared to cells in the control knockdown group, while ectopic expression of GDF15 hindered viability of these tumor cells." (PMID 38082448, 2023). "Moreover, 12 of 25 patients with high sLDH (and presumably high tumor load) and low GDF-15 were still alive at the end of the observation period, while no long-term survivors were among the 6 patients with low sLDH and high GDF-15." (PMID 37474523, 2023). "Indeed, we show that silencing GDF15 expression in PSC rescues its effect on MAGEA2-mediated chemoresistance in tumor cells." (PMID 37814317, 2023). "In summary, our results indicated that GDF15 is an important tumor suppressor gene in ccRCC." (PMID 38082448, 2023). "GDF-15 blockade further enhances T cell trafficking to tumor-draining lymph nodes." (PMID 37474523, 2023). "Low availability of T cells in GDF-15-expressing tumours thus precludes effective immune therapy." (PMID 37474523, 2023). "Together, these data indicated that Gem stimulated PSCs could regulate the chemosensitivity of MAGEA2-expressing tumor cells via the GDF15-GFRAL mediated paracrine signaling." (PMID 37814317, 2023). "Tumor-bearing mice were treated with anti-GDF-15 on day 6, 9, and 12 after tumor implantation." (PMID 37474523, 2023). "It is therefore reasonable to speculate that HIF1 stimulates both GDF15 expression and exosome release in tumor cells, resulting in increases in circulating GDF15 that contributes to CC." (PMID 36672227, 2023). "Still, by interfering with T cell adhesion to activated human endothelial cells, GDF-15 may reduce T cell infiltration into tumor tissue." (PMID 37474523, 2023).
tumor (continued). "Other data show that prostate cancer may stimulate the release of GDF15 from osteocytes to alter the tumor microenvironment and promote metastasis." (PMID 36672227, 2023). "Similarly, depletion of GDF-15 in orthotopic pancreatic cancer models restored immunosurveillance in the TME resulting in improved tumor control." (PMID 35743911, 2022). "The process behind the development of osteoblastic metastases is still largely unknown but it seems to be related to the tumor production of osteoblastic factors, such as ET-1, growth differentiation factor 15, and bone morphogenic proteins." (PMID 35205641, 2022). "Notably, the level of GDF-15 in C26 tumor tissues was significantly higher than that of MC38 tumor tissues." (PMID 35379793, 2022). "We hypothesize that enhanced GDF-15 correlation with tumor response in this study is due to the direct relationship between the drug target and its substrate processing, making secreted GDF-15 a PACE4 target-engagement biomarker." (PMID 36261691, 2022). "It has been hypothesized that GDF-15 primarily performs a tumor-suppressing function in the early stages of tumor development, and then a tumor-promoting function in the later stages." (PMID 35872912, 2022). "In HCC, GDF15 has shown both tumour-promoting and anti-tumour effects." (PMID 35264787, 2022). "When we translate this hypothesis into the clinical setting, we predict that the down-regulation of GDF15 expression in a tumor responding to eribulin would anticipate the progression of the disease." (PMID 35626166, 2022). "Skeletal muscle and adipose tissue wasting in CAC is associated with an increase in various factors that derive from host or tumour cells to ascertain key factors in our cachectic mouse model, serum activin A, GDF15, and other inflammatory factors were measured." (PMID 35044098, 2022). "Additionally, a recent study showed that treatment with a GDF15-neutralizing antibody in combination with cisplatin improves survival in a mouse tumor model." (PMID 35626166, 2022). "PD-L1 expression correlates with response to immunotherapy in certain tumor types, and neutralization of GDF-15 activity could be a possible treatment to extend the benefits of immunotherapy in patients with solid cancers and metastases." (PMID 36230513, 2022). "Interestingly, despite low levels of GDF-15 secreted by the JHU-LNCaP-SM cells in vitro, when xenografted they clearly secrete significant amount of circulating GDF-15 which even correlate better with tumor size than PSA." (PMID 36261691, 2022). "Besides, GDF15 plays a vital role in metabolic disorders, inflammatory process, tumor progression, and interestingly, neurodegenerative diseases." (PMID 35860670, 2022). "Patients with high plasma level of GDF-15 had significantly larger tumour volume (p = 0.008)." (PMID 34951691, 2022). "However, the role of GDF-15 is still controversial, depending on the tumor entity and model studied." (PMID 35300113, 2022). "Therefore, further studies are required to examine the interaction of GDF15 with other components of the tumor microenvironment, including macrophages and fibroblasts." (PMID 35280749, 2022). "GDF15 expression in epithelial cells was negatively correlated with neoplasia in vitro." (PMID 34662721, 2022). "However, GDF15 has also been found to stimulate tumor immunity, as its overexpression was correlated with increased populations of activated CD8+ T cells in murine models of prostate cancer." (PMID 36353620, 2022). "This could be because by day 21 the tumor size in milademetan-treated animals was already reduced, leading to decreased levels of secreted human GDF-15." (PMID 35801592, 2022). "GDF15 expression is elevated in tumor cells and increases with progression, especially in CRPC." (PMID 36361635, 2022). "It will be interesting to examine whether circulating GDF15 and GDF15 produced locally in the bone microenvironment by tumor or stromal cells play similar or distinct roles in promoting PCa bone metastasis." (PMID 35058441, 2022).
tumor (continued). "GDF-15 is released from tumor cells and can be detected by analyzing serum or plasma samples." (PMID 35801592, 2022). "Based on this findings, we thought that high liver GDF15 expression might affect the tumor development and/or progression in thyroid glands." (PMID 36046792, 2022). "The discrepancy between tumor mRNA expression and circulating level of GDF-15 may involve the ratio of patients with metastasis in each study population." (PMID 34638326, 2021). "Enriched type 1 T-helper (Th1), enriched regulatory T (Treg), enriched eosinophils, and decreased nature killer T-cells (NKTs) in COAD tumor tissue may play counteracting factors on the tumor-regulatory effects of miR-216a and GDF15." (PMID 34948431, 2021). "We confirmed that the protein expression of p-ERK and p-AKT in tumor tissues synergistically decreased along with GDF15 and EGR1 in the combined treatment group compared to the single treatment groups, whereas the total level of AKT and ERK protein were not affected." (PMID 34681812, 2021). "Moreover, loss of TK1 results in a loss of GDF15, one of the TGF-beta ligands, leading to reduced tumor activity and metastasization." (PMID 34830698, 2021). "Moreover, combined inhibition of both GDF15 and EGR1 in a HNC mouse xenograft model showed significantly decreased tumor volume compared to inhibition of EGR1 or GDF15 alone." (PMID 34681812, 2021). "Furthermore, the authors demonstrated that pair feeding 3P10-treated tumor-bearing mice to IgG-control tumor-bearing mice still led to a significant improvement in body mass, revealing a food-intake independent mechanism of GDF15 during cancer cachexia." (PMID 34439145, 2021). "Next, we examined the effects of the silencing of NR5A2 and GDF15 on tumor growth in vivo." (PMID 33850096, 2021). "Furthermore, tumor‐derived GDF‐15 inhibits the synthesis of nitric oxide and TNF‐α through TGF‐activated kinase‐1 in macrophages." (PMID 33738380, 2021). "Given the complexity of the immune system network and the multidimensionality of host‐tumor interactions, NF‐κB and GDF‐15 may be signature molecules that can elucidate the molecular kinetics of inflammatory responses early in prostatic carcinogenesis." (PMID 33784024, 2021). "A previous study showed that in human prostate GDF‐15 suppresses the activity of NF‐κB, indicating a tumor‐suppressing quality, but it may also preferentially inhibit M1 macrophage formation, indicating a pro‐tumorigenic quality." (PMID 33784024, 2021). "GDF‐15 may suppress the activity of NF‐κB, indicating a tumor‐suppressing quality, but has also been shown to preferentially inhibit M1 macrophage formation, indicating a pro‐tumorigenic quality." (PMID 33784024, 2021). "It has previously been suggested that GDF15 may act as a tumor suppressor at the early stages of tumor development and progression, and later becoming a tumor promoter as the tumor progresses into a malignant phenotype 50." (PMID 34149933, 2021). "GDF15 has been reported to be a pivotal regulator of tumor cell invasion and metastasis and could promote ferroptosis in tumor cells." (PMID 34249766, 2021). "Researchers also uncovered that whether GDF15 is an oncogene or a suppressor gene of tumor growth appears to be depending on the cancer cell type, the stage of the cancer, as well as the location of GDF15 in cancer cells." (PMID 34681812, 2021). "We therefore speculate that increased solid stress due to a large tumor burden augments the expressions of pJNK and pAKT and also increases levels of circulating GDF-15." (PMID 34638326, 2021). "JMJD1A increases or maintains expression of certain genes under hypoxia by reducing H3K9 demethylation of specific hypoxia-responsive promoters, including ADM, EDN1, HMOX1, and GDF15, resulting in increased expression of these genes and favouring tumour cell growth." (PMID 34572020, 2021).